CPT2 (carnitine palmitoyltransferase 2)
Diseases named in the same sentence as CPT2 in open-access papers (continued):
Sharing a sentence is not in itself a finding about the gene and the disease.
steatosis (11 papers, 2016 to 2025). Increased lipid within the cytoplasm of cells. "A liver-specific defect in adipose triglyceride lipase (ATGL) or carnitine palmitoyltransferase 2 (CPT2) results in steatosis and the loss of both components leads to significant steatohepatitis upon high-fat feeding." (PMID 34680522, 2021). "Conversely, serum miRNAs associated with blunt steatosis specifically highlighted activity of FOXO1&HNF4α on CPT2, the lipid droplet and ER-lipid-raft associated PLIN3 and Erlin1." (PMID 27045805, 2016). "Finally, the loss of TG hydrolysis or fatty acid oxidation alone is sufficient for the generation of steatosis; however, the loss of both Atgl and Cpt2 is required for the generation of significant steatohepatitis." (PMID 33491665, 2021). "However, high-fat feeding revealed the interdependent role of Atgl and Cpt2 as the loss of only one of the genes resulted in steatosis; however, loss of both components resulted in significant steatohepatitis." (PMID 33491665, 2021). "However, high-fat feeding revealed the interdependent role of Atgl and Cpt2, as the loss of only one of the genes resulted in steatosis (fatty liver) but the loss of both components resulted in significant steatohepatitis (inflammation and fibrosis)." (PMID 33491665, 2021). "PPARα restoration led to the transcriptional activation of genes associated with lipid metabolism, including carnitine palmitoyltransferase 2 (CPT2) and acyl-CoA binding domain containing 3 (ACBD3), and then resulted in the steatosis resolution." (PMID 29018509, 2017). "Furthermore, steatosis induction resulted in a significant upregulation of CPT2 in male PHHs only." (PMID 41301863, 2025). "When the level of PPARα is increased, its target gene carnitine palmitoyltransferase 2 (CPT2) and the acyl-CoA binding domain containing 3 (ACBD3) or the solute carrier family 27A (SLC27A) are activated, and the steatosis is reduced." (PMID 30931332, 2019). "Our steatosis model exhibited no significant impact on either Carnitine palmitoyltransferase 1a (CPT1a) or Carnitine palmitoyltransferase 2 (CPT2) expression." (PMID 38474427, 2024). "In this study, only CPT2 was overexpressed, but in a previous study, we reported that the intake of lycopene from tomato juice increased the mRNA abundance of CPT1A, together with the carnitine content, in the liver of rats with steatosis." (PMID 30987167, 2019).
colorectal cancer (10 papers, 2020 to 2024). A primary or metastatic malignant neoplasm that affects the colon or rectum. "In contrast, downregulation of CPT2 was found to be associated with poor prognosis and tumorigenesis in colorectal cancer and HCC." (PMID 37601653, 2023). "We identified 236 metabolism-related genes that are differentially expressed in colorectal cancer, of which 49 up-regulated and 187 down-regulated, and found CPT2 as the most significant gene associated with favorable prognosis in CRC." (PMID 36195841, 2022). "Our study meticulously utilized single-cell sequencing to pinpoint ACOX1 and CPT2 as pivotal oncogenes in the nucleotide metabolism of colorectal cancer." (PMID 38594466, 2024). "We evaluated the expression of ACOX1 and CPT2 in 80 pairs of colorectal cancer tissues and adjacent normal tissues using IHC methods." (PMID 38594466, 2024). "In colorectal cancer tissues, carnitine palmitoyltransferase 2 (CPT2) expression is downregulated, activating the ROS/Wnt/β-catenin pathway and inducing oxaliplatin resistance in colorectal cancer." (PMID 35684449, 2022). "We used 28 colorectal cancer and paired adjacent normal tissues and found that CPT2 expression was downregulated in tumor (p = 0.0027)." (PMID 36177002, 2022). "Little is known about the deregulation of CPT2 in cancer; however, a recent study reported that this enzyme can be considered as an independent prognostic factor in colorectal cancer patients." (PMID 34679988, 2021). "Together, these findings suggest that ACOX1 and CPT2 are oncogenes for colorectal cancer." (PMID 38594466, 2024). "Moreover, Colorectal cancer stemness and oxaliplatin resistance are induced by CPT2 downregulation, which potentiates glycolytic metabolism mediated by ROS/Wnt/β-Catenin pathways." (PMID 37205121, 2023). "Furthermore, the downregulation of CPT2 in colorectal cancer induces stemness and drug resistance by activating glycolytic metabolism induced by the ROS/Wnt/β‐linked protein pathway." (PMID 36776001, 2023). "In addition, the downregulation of CPT2 in colorectal cancer can promote cancer stemness and oxaliplatin (chemotherapy drug) resistance through the activation of the Wnt/β-catenin pathway by inducing glycolytic metabolism." (PMID 37601653, 2023). "Secondly, we did not further explore the mechanism of how CPT2 inhibits the proliferation of colorectal cancer cells, and how it plays a metabolic function in the progression of CRC." (PMID 36195841, 2022).
ovarian carcinoma (9 papers, 2021 to 2024). A malignant neoplasm originating from the surface ovarian epithelium. "In COAD, downregulation of CPT2 promotes tumor resistance to oxaliplatin, while in ovarian cancer, downregulation of CPT2 promotes tumor growth and metastasis." (PMID 36177002, 2022). "Our results are also consistent with those of Zhang X. and coworkers (2021), who demonstrated downregulation of CPT2 in ovarian cancer (OC) cells and a poorer prognosis for patients with OC." (PMID 34679988, 2021). "Importantly, a recent report showed that the inhibition of CPT2 strongly supported metastasis formation and poor prognosis in a pool of human ovarian cancer patients." (PMID 38196068, 2024). "Furthermore, the downregulation of carnitine palmitoyltransferase 2 (CPT2) induces the ROS/NF-κB pathway in ovarian cancer to promote tumor growth and metastasis." (PMID 38474405, 2024). "The elevated expressions of key rate-limiting FAO-related enzymes, such as fatty acyl-CoA synthetase, CPT1, carnitine palmitoyltransferase 2 (CPT2), are essential for the upregulation of FAO, which may herald a poor prognosis in acute myeloid leukemia and ovarian cancer." (PMID 34603046, 2021).
CACT deficiency (8 papers, 2018 to 2025). "CPT1 deficiency (CPT1D), CPT2 deficiency (CPT2D), and CACT deficiency (CACTD) are rare autosomal inherited recessive disorders, and the causative genes are CPT1A, CPT2, and SLC25A20, respectively." (PMID 35360862, 2022). "The C2/(C16+C18:1) ratio is used as an index for diagnosing carnitine palmitoyltransferase-2 (CPT2) deficiency (OMIM 600650) and carnitine-acylcarnitine translocase (CACT) deficiency (OMIM 212138)." (PMID 30133480, 2018).
Hepatic steatosis (8 papers, 2017 to 2025). Steatosis is a term used to denote lipid accumulation within hepatocytes. "Acyl-CoA produced by Acyl-CoA synthase long chain (ACSL1), which is not used for acyl-carnitine shuttling via CPT1, CACT and CPT2, could also be re-esterified to triacylglycerol and deposited in the liver cells causing hepatic steatosis." (PMID 30337593, 2018). "Under ER stress conditions, ATF6α knockout mice exhibited hepatic steatosis due to the inhibition of fatty acid β-oxidation, and was accompanied by reduced expression of the related genes, including PPARα, CPT1, CPT2 and ACOX1." (PMID 30081561, 2018). "In consistent with their facilitatory role in lipid degradation, circRNA_0046367-induced normalization of both CPT2 and ACBD3 resultantly attenuated the hepatic steatosis by statistical downregulation of TG content." (PMID 29018509, 2017).
Encephalopathy (7 papers, 2014 to 2022). Encephalopathy is a term that means brain disease, damage, or malfunction. "Encephalopathy caused by genetic abnormalities such as CPT2 and SCN1A is also being studied." (PMID 36233788, 2022). "Polymorphisms of CPT2, a carnitine palmitoyltransferase 2 protein, were found in patients suffering from influenza-associated encephalopathy; results of overexpression of CPT2 variants in vitro suggested that the variants were heat-labile and failed to perform optimally during fever." (PMID 27156515, 2016).
Myalgia (7 papers, 2019 to 2023). "The CPT2 variant was also found in two of his sisters, and one of them had a history of elevated CK and myalgias." (PMID 35572607, 2022). "CPT2: wo patients (8/A, 9/A) carried rare variants in CPT2 (Carnitine Palmitoyl Transferase 2, OMIM*600650), either homozygous or possibly compound heterozygous; both presented with myalgia and exercise intolerance, myoglobinuria, and RM." (PMID 37510298, 2023).
Arrhythmia (6 papers, 2018 to 2025). Any cardiac rhythm other than the normal sinus rhythm. "Further, cardiac arrhythmia and sudden death are also reported in children with other fatty acid oxidation defects such as defective carnitine palmitoyl transferase 2 (CPT2) and carnitine fatty acyl-CoA translocase and MTP deficiency." (PMID 29361796, 2018). "Among the four genes, UCP2, UCP3, and CPT2 played a crucial role in fatty acid oxidation, it has proven that the downregulation of UCP2 and UCP3 impaired myocardial fatty acid oxidation and elevates the production of reactive oxygen species (ROS), subsequently increasing the incidence of arrhythmia." (PMID 38283583, 2024).
Insulin resistance (6 papers, 2017 to 2025). Increased resistance towards insulin, that is, diminished effectiveness of insulin in reducing blood glucose levels. "Loss of muscle CPT2 results in a high degree of long-chain acylcarnitine accumulation, which has been shown to protect against diet-induced obesity and insulin resistance." (PMID 39781464, 2025). "The upregulation of SIRT2 expression improves insulin resistance, cell apoptosis, and cardiac dysfunction, mainly by deacetylating and disrupting CPT2 expression." (PMID 39781464, 2025). "SIRT2 overexpression decreased CPT2 protein expression and promoted insulin resistance, cell apoptosis, and cardiac dysfunction both in vivo and in vitro." (PMID 39781464, 2025). "CPT2 knockout mice was resistance to weight gain, glucose intolerance, insulin resistance, and impairments in insulin-induced Act phosphorylation during following a high-fat diet." (PMID 34938272, 2021). "Furthermore, inhibition of carnitine acyltransferases CPT-1 and CPT-2, resulting in inhibition of medium and long chain acylcarnitine synthesis and accumulation, prevents fatty acid-induced insulin resistance in muscle." (PMID 28420087, 2017).
McArdle disease (6 papers, 2007 to 2026). "The most commonly identified predisposing conditions of ER are deficiencies of carnitine palmitoyltransferase II (CPT2 gene, OMIM *600650), myophosphorylase (McArdle disease, PYGM gene, OMIM *608455), and myoadenylate deaminase (AMPD1 gene, OMIM +102770)." (PMID 23476141, 2013).
acute kidney injury (5 papers, 2019 to 2024). Sudden and sustained deterioration of the kidney function characterized by decreased glomerular filtration rate, increased serum creatinine or oliguria. "Herein, we report the case of a male patient who developed exertional rhabdomyolysis and acute kidney injury due to CPT2 deficiency." (PMID 39473663, 2024).
cardiac hypertrophy (5 papers, 2020 to 2023). "CPT2, with its oxidative bioenergetic role, when deficient, can inhibit long-chain fatty acid oxidation, ushering in cardiac hypertrophy." (PMID 37950149, 2023). "Here, we tested the ability of the medium-chain fatty acid octanoate to improve CPT2 deficiency-induced cardiac hypertrophy." (PMID 33757734, 2021). "Specifically, we have shown that unlike hypertension-induced and ischemia-induced models, the cardiac hypertrophy triggered by CPT2 deficiency is resistant to attenuation by rapamycin, an mTor inhibitor, and by trichostatin A, a deacetylase inhibitor." (PMID 33757734, 2021). "The CPT2-deficient mouse model developed cardiac hypertrophy and systolic dysfunction, with a significant reduction in blood ejection fraction." (PMID 33166306, 2020). "Here, we explored the ability of octanoate, an eight-carbon medium-chain fatty acid known as an unregulated mitochondrial energetic substrate, to ameliorate cardiac hypertrophy in long-chain fatty acid oxidation-deficient hearts because of carnitine palmitoyltransferase 2 deletion (Cpt2M−/−)." (PMID 33757734, 2021). "Surprisingly, a heavily octanoate-enriched ketotic diet was not able to alleviate CPT2 deficiency-mediated cardiac hypertrophy." (PMID 33757734, 2021). "Together, these data demonstrate that the octanoate-rich diet modulates cardiac function of control mice, an effect that Cpt2M−/− mice are impervious to, and that octanoate diet fails to alleviate cardiac hypertrophy or to improve cardiac function in CPT2-deficient hearts." (PMID 33757734, 2021).
metabolic myopathies (5 papers, 2007 to 2025). "The rheumatologist suspected a metabolic myopathy and the patient underwent a metabolic myopathy panel, which showed elevated levels of hexadecanoylcarnitine (C16) and octadecanoylcarnitine (C18), a common finding in patients with CPT2 deficiency." (PMID 39850164, 2024).
triple-negative breast carcinoma (5 papers, 2020 to 2025). An invasive breast carcinoma which is negative for expression of estrogen receptor (ER), progesterone receptor (PR), and human epidermal growth factor receptor 2 (HER2). "Another study revealed that SYVN1 ubiquitylates CPT2 to inhibit fatty acid oxidation and tumorigenesis in triple-negative breast cancer." (PMID 37816756, 2023). "At present, it has only been reported that HRD1 is the E3 ligase of CPT2 in triple-negative breast cancer, and whether there are other E3 ligases or deubiquitinating enzymes in CPT2 is still unclear." (PMID 39596847, 2024). "On the contrary, like our findings in CRC, it was also reported that CPT2 played an oncogenic function in triple-negative breast cancer (TNBC) cells, suggesting that CPT2 may play distinct functions in different types of cancer." (PMID 40592838, 2025). "Indeed, metastatic triple-negative breast cancer (TNBC) cells maintain a high level of ATP production through the activation of mitochondrial FAO and carnitine-palmitoyltransferases 1 and 2 (CPT1 and CPT2), trans-membrane enzymes located in outer and inner mitochondrial membranes, respectively." (PMID 32252351, 2020).
colon cancer (4 papers, 2021 to 2025). "There is a negative correlation between CPT2 expression and tumor stage, while low expression of CPT2 is associated with poor prognosis in colon cancer." (PMID 38921447, 2024). "In colon cancer, CPT2 expression is negatively correlated with tumor stage and low expression of CPT2 is associated with poor prognosis." (PMID 33530546, 2021). "In addition to the gene-metabolite map, we determined that the expression of CPT2 was significantly increased (6.56) in left colon cancer based on RT-qPCR results." (PMID 41441010, 2025).
Hypoglycemia (4 papers, 2018 to 2026). A decreased concentration of glucose in the blood. "Defective CPT2 impairs mitochondrial fatty acid utilization, reducing energy production from fats and increasing risk of hypoglycemia; ketogenic diets are therefore contraindicated." (PMID 41486865, 2026). "Importantly, both CPT-2 and peroxisomal deficiencies, well known inborn errors of metabolism, are associated with hypoglycemia in afflicted patients." (PMID 30167086, 2018).
multiple acyl-CoA dehydrogenase deficiency (4 papers, 2021 to 2025). "One child affected with both CPT2 and MAD deficiencies was also identified, caused by bi-allelic variants in both CPT2 and FLAD1." (PMID 40981303, 2025). "In addition, other types of genetic metabolic diseases were also detected, such as hyperhomocysteinemia, MCADD, MMA, propionemia, 3-hydroxy-3-methylglutaric acidemia, ornithine carbamoyltransferase deficiency, H-TYR, CPS1, CPT2, and glutaric acidemia type II." (PMID 34394177, 2021). "Further, six cases of fatty acid metabolism disorder (1/1,244) were found, including two cases of PCD (1/3,731), two cases of SCADD (1/3,731), one case of carnitine palmitoyltransferase II deficiency (CPT2; 1/7,461), and one case of glutaric acidemia type II (1//7,461)." (PMID 34394177, 2021).
colon adenocarcinoma (3 papers, 2022 to 2023). "While low expression of SUCLG2 (p < 0.001), PTGR1 (p = 0.001), ELOVL6 (p = 0.013) and CPT2 (p < 0.001) were correlated with poor overall survival of colon adenocarcinoma patients." (PMID 36568396, 2022). "Results showed increased expression of ENO3, MORC2, SUCLG2 and ELOVL6, and decreased expression of CPT2 in all examined colon adenocarcinoma cell lines." (PMID 36568396, 2022). "Moreover, qRT-PCR revealed upregulated expression of ENO3, MORC2, SUCLG2 and ELOVL6, and downregulated expression of CPT2 in all examined colon adenocarcinoma cell lines." (PMID 36568396, 2022).
deficiencies (3 papers, 2023 to 2025). "Although the finding of fetal malformations is exceptional in FAO congenital disorders, in the case of CPT2 or multiple acyl-coA dehydrogenase (MADD) deficiencies, cerebral anomalies, or polycystic kidneys have been described." (PMID 37764661, 2023).
gastric cancer (3 papers, 2021 to 2025). A primary or metastatic malignant neoplasm involving the stomach. "Gastric cancer and CRC patients with lower CPT2 expression level have better disease control rates than those with higher CPT2 expression." (PMID 34740325, 2021). "SLC25A42 promotes the growth of gastric cancer (GC) cells while suppresses ferroptosis by reprograming lipid metabolism through elevating the acetylation and thus expression of CPT2, implying that SLC25A42 could serve as a potential therapeutic strategy for the treatment of this malignancy." (PMID 40246810, 2025).
glioma (3 papers, 2022 to 2024). A benign or malignant brain and spinal cord tumor that arises from glial cells (astrocytes, oligodendrocytes, ependymal cells). "Five genes associated with the prognosis of glioma (ECI2, MCCC2, OXCT1, SUCLG2, and CPT2) were revealed and then, validated using glioma tissues, providing novel insights into individualized treatment and prognosis." (PMID 39491527, 2024). "This study revealed five genes associated with the prognosis of glioma (ECI2, MCCC2, OXCT1, SUCLG2, and CPT2), providing novel insights into individualized treatment and prognosis." (PMID 39491527, 2024). "ECI2, MCCC2, OXCT1, SUCLG2, and CPT2 were identified as prognostic genes for glioma." (PMID 39491527, 2024). "Most cellular metabolism genes investigated in glioma cell lines (ATP5A1, COX5A, CPT2, PFKL, and UQCRFS1) were found to be statistically downregulated." (PMID 36142793, 2022). "IHC analysis revealed that the three essential FAO enzymes CPT1A, CPT2, and ACAD9 were increased 86.96, 84.78, and 76.09% respectively in the recurrent gliomas, companied with 82.6% CD47 enhancement." (PMID 35314680, 2022).